MAOA (monoamine oxidase A)
Diseases named in the same sentence as MAOA in open-access papers (continued):
Sharing a sentence is not in itself a finding about the gene and the disease.
diabetes (12 papers, 2017 to 2025). "Older adults diagnosed with diabetes mellitus, systemic arterial hypertension, or both (DM/SAH) were selected and had their MAOA gene genotyped for uVNTR polymorphism." (PMID 37533936, 2023).
gastric cancer (12 papers, 2008 to 2025). A primary or metastatic malignant neoplasm involving the stomach. "Monoamine oxidase A (MAO-A) modulates mitochondrial function and glycolysis, inhibiting gastric cancer cell proliferation and metastasis." (PMID 41220952, 2025). "In gastric cancer, MAOA (monoamine oxidase A) is generally downregulated, but its re-expression has been shown to suppress the PI3K/Akt/mTOR pathway via interaction with NDRG1." (PMID 41220952, 2025). "By assessing MAOA expression levels and muscle-fat features, we can more accurately predict long-term survival in gastric cancer patients and provide evidence for tailoring different treatment strategies." (PMID 39010072, 2024). "Studies have also indicated that MAOA expression is significantly downregulated in gastric cancer tissue." (PMID 39010072, 2024). "MAOA was found to be involved in mitochondrial dysfunction, and promoted malignant growth and metastasis in gastric cancer." (PMID 36915111, 2023). "Monoamine oxidase A (MAO-A) is a mitochondrial protein that is up-regulated in gastric cancer cells." (PMID 36438836, 2022). "The norepinephrine levels were markedly high in gastric cancer tissue, while the norepinephrine-degrading enzymes MAOA and MAOB showed low expression." (PMID 33855088, 2021). "However, the GEPIA analysis revealed that both MAPK1 and ICAM1 were highly expressed in gastric cancer tissues, whereas MAOA expression was relatively low." (PMID 40283909, 2025). "MAOA emerges as an independent prognostic factor for gastric cancer patients." (PMID 39010072, 2024). "We identified only two relevant articles concerning MAOA in gastric cancer." (PMID 39010072, 2024). "Given that PET-CT of gastric cancer patients could represent glycolysis activity in patients, we evaluated MAOA and MAOB expression using patient PET-CT graphics." (PMID 33855088, 2021). "However, the role of body composition (muscle and fat) parameters and MAOA in predicting prognosis for advanced gastric cancer (AGC) patients remains unknown." (PMID 39010072, 2024). "Another study mentioned that MAOA can interact with NDRG1, inhibiting downstream PI3K/AKT/mTOR pathway activity, thereby attenuating the Warburg effect in gastric cancer cells and ultimately suppressing tumor cell proliferation and malignant behavior." (PMID 39010072, 2024). "Both MAOA and MAOB showed low expression in gastric cancer tissue compared with that in normal tissue." (PMID 33855088, 2021). "Secondly, our research focused solely on the role of the MAOA gene and imaging features in predicting gastric cancer patients’ long-term survival without considering other potential biomarkers." (PMID 39010072, 2024). "Subsequently, NE synthetase enzymes tyrosine hydroxylase (TH), dopa decarboxylase (DDC), and dopamine-β-hydroxylase (DBH), degrading enzymes monoamine oxidase A and B (MAOA and MAOB), and catechol-O-methyl transferase (COMT) were analyzed in TCGA database of gastric cancer." (PMID 33855088, 2021). "Finally, the clinicopathological characteristics of gastric cancer patients, such as PD-L1 expression, the microsatellite status, TNM stage, pathology type, and tumor diameter, were analyzed in 52 patients with MAOA expression." (PMID 33855088, 2021). "However, this study did not delve into the molecular mechanisms of MAOA in gastric cancer development or consider its expression in gastric cancer tissues for clinical relevance." (PMID 39010072, 2024). "Moreover, the immunohistochemistry results from HPA database showed that FKBP10 was upregulated in gastric cancer tissues, while ALDH3A2 and MAOA were downregulated in gastric cancer tissues, when compared with corresponding non-cancerous tissues." (PMID 36915111, 2023).
gastric cancer (continued). "The Gene Expression Omnibus (GEO) database has suggested a significant downregulation of MAOA in several cancerous tissues (such as lung cancer, kidney cancer, pulmonary adenocarcinoma, gastric cancer, and early hypopharyngeal cancer), compared with non-cancerous control tissues." (PMID 34209963, 2021). "The norepinephrine-degrading enzymes MAOA and MAOB have significant expression differences in cancer and normal tissue, and their missing or low expression may predict immune therapy outcomes for gastric cancer patients." (PMID 33855088, 2021).
migraine (12 papers, 2009 to 2025). "Risk variants and haplotypes in dopamine metabolism genes, DBH, DDC, MAOA, and SLC6A3, are reported to influence migraine risk, as are variants in the oestrogen receptor gene, ESR1." (PMID 22030984, 2011). "In summary, our results do not support the involvement of a set of dopamine-related genes in the genetic vulnerability to migraine in the Spanish population, albeit a previous association study in the same cohort identified DDC and MAOA as potential susceptibility genes." (PMID 19772578, 2009). "We previously reported risk haplotypes for two genes related with serotonin and dopamine metabolism: MAOA in migraine without aura and DDC in migraine with aura." (PMID 19772578, 2009).
hepatocellular carcinoma (11 papers, 2020 to 2026). A malignant tumor that arises from hepatocytes. "In contrast, a positive correlation was reported between MAOA and favourable prognosis in patients with hepatocellular carcinoma, where MAOA was found to suppress HCC metastasis." (PMID 38520217, 2024). "MAOA also serves as a potential therapy target of traditional Chinese medicine nitidine chloride in hepatocellular carcinoma patients." (PMID 32931665, 2020). "In contrast to its oncogenic roles, in hepatocellular carcinoma (HCC), MAOA was linked to better patient prognoses and was found to suppress metastasis by inhibiting the adrenergic system and its transactivation of epidermal growth factor receptor (EGFR) signaling." (PMID 41338163, 2025). "MAOA was also downregulated in hepatocellular carcinoma patients." (PMID 36902343, 2023). "MAOA inhibits the metastasis of hepatocellular carcinoma cells by suppressing the adrenergic system and activating the epidermal growth factor receptor (EGFR) signaling pathway, showing a negative correlation with hepatocellular carcinoma progression." (PMID 40225029, 2025).
lung carcinoma (11 papers, 2009 to 2025). "Bioinformatics analysis found that MAOA might be a potential target of diagnosis and treatment for lung cancer." (PMID 32792865, 2020). "Additionally, it was reported that MAOA might promote the metastatic potential of lung cancer cells." (PMID 32792865, 2020). "Furthermore, our study investigated the relationship between IPF-ARGs and lung cancer, identifying CDH3 as an oncogenic gene and recognizing EDNRB, MAOA, and PLA2G1B as tumor suppressor genes." (PMID 40589973, 2025).
attention deficit-hyperactivity disorder (10 papers, 2007 to 2024). A disorder characterized by a marked pattern of inattention and/or hyperactivity-impulsivity that is inconsistent with developmental level and clearly interferes with functioning in at least two settings (e.g. at home and at school). "There is also genetic evidence for MAOA in attention deficit hyperactivity disorder (ADHD), a disorder observed in individuals with 47,XXY." (PMID 34210361, 2021). "We also studied the MAOA candidate gene and addressed comorbid attention-deficit/hyperactivity disorder (ADHD)." (PMID 30569215, 2019).
nicotine dependence (10 papers, 2011 to 2025). Physical and psychological dependence on nicotine. "From a physiological standpoint, smoking likely enhances impulsive behaviors, raising suicide risk via pathways involving serotonin regulation, MAOA gene variants, and nicotine dependence." (PMID 40565498, 2025). "Another genetic investigation showed that the interaction between uVNTR and dVNTR in the monoamine oxidase A (MAOA) gene was significantly associated with nicotine dependence." (PMID 33784353, 2021). "The pathways in nicotine addiction play a pivotal role in sustaining substance use disorders, particularly in smokers experiencing depressive symptoms modulated by the monoamine oxidase-A (MAO-A) enzyme." (PMID 38397715, 2024).
prostate tumor (10 papers, 2014 to 2025). "In the study of prostate tumors (PCa), the increased expression of monoamine oxidase A (MAOA) promoted the production of epithelial-to-mesenchymal transition (EMT), hypoxia, and ROS, which jointly promoted the tumorigenesis, development, and metastasis of PCa." (PMID 32391293, 2020). "We previously found that MAOA expression correlated with prostate tumor cell differentiation status, with higher MAOA levels associated with higher Gleason patterns." (PMID 25198178, 2014).
bipolar disorder (9 papers, 2008 to 2025). A disorder of the brain that causes unusual shifts in mood, energy, activity levels and the ability to carry out day-to-day tasks. "Dinucleotide repeat variants in intron 2 of the human MAOA gene have been associated with female bipolar disorder." (PMID 28101368, 2017). "Although several pieces of evidence suggested that MAOA is important in the etiology of bipolar affective disorder (BPD), associations for markers of the MAOA gene with BPD were not conclusive and the association has not been investigated in Taiwanese population." (PMID 18501009, 2008). "Among these were BDNF, VGF, WFS1, DUSP6, CRHBP, MAOA, and RELN, which have previously been implicated in bipolar disorder." (PMID 31114610, 2019).
glioblastoma (8 papers, 2017 to 2025). The most malignant astrocytic tumor (WHO grade IV). "A case–control study indicated that MAOA polymorphisms (rs144551722 SNP) were a significant biomarker of glioblastoma development in men." (PMID 34209963, 2021). "In line with the reasoning presented above, the purpose of the present study was to investigate the specific hypothesis that variation in the MAOA gene is associated with development of glioblastoma in males." (PMID 31556016, 2019). "In the analysis of MAOA polymorphism, a large case–control study indicated that the rs144551722 SNP of MAOA was a significant predictor of development of glioblastoma in men (p = 0.0056), but not in women, even after correction for multiple testing." (PMID 34209963, 2021). "Taken as a whole our results support the hypothesis that MAOA-genotype may play a role in development of glioblastoma in males." (PMID 31556016, 2019).
Hypertension (8 papers, 2017 to 2023). The presence of chronic increased pressure in the systemic arterial system. "In vivo, MAOA was induced during aging and hypertension but the expression of the corresponding serotonin uptake receptor (SLC6A4) was reduced and enzymes that reduce either oxidative stress (CAT) or accumulation of 5-hydroxyindolacetaldehyde (ALDH2) were induced." (PMID 37371593, 2023).
Intellectual disability (8 papers, 2017 to 2025). "Brunner syndromeis a rare genetic disorder characterized by impulsiveaggressiveness and intellectual disability, which is linked to impairedfunction of the monoamine oxidase A (MAO-A) enzyme." (PMID 40135540, 2025). "SNVs in exon 8 have been associated with Brunner’s disease in humans, a rare recessive X-linked disorder characterized by impulsive aggressiveness and mild mental retardation associated with MAOA deficiency." (PMID 28101368, 2017). "Later on, other missense mutations in the MAOA gene were found in several families and individuals sharing a similar clinical picture that included autism spectrum disorder, aggressive behavior, attention deficit disorder and intellectual disability." (PMID 36536002, 2022). "Monoamine oxidase A (MAO‐A) deficiency is a rare inborn error of metabolism with impaired degradation of biogenic amines including 5‐hydroxytryptamine (5‐HT), resulting in borderline intellectual disability and behavioral abnormalities." (PMID 33728254, 2021).
serotonin syndrome (8 papers, 2010 to 2025). Serotoninergic syndrome is characterized by an excess of serotonin in the central nervous system, associated with the use of various agents, including selective serotonin reuptake inhibitors (SSRIs). "Drug-drug interactions can occur with serotonergic and adrenergic agents due to linezolid being a weak, non-selective, reversible inhibitor of monoamine oxidase A and B. A review of serotonergic interactions with linezolid found the incidence of serotonin syndrome was 0.24% to 4%." (PMID 34842791, 2021). "Interestingly, there is a report of paradoxical reaction regarding fentanyl use in the treatment of serotonin syndrome, which had been induced by coadministration of the selective serotonin reuptake inhibitor (SSRI) fluoxetine and the reversible inhibitor of monoamine oxidase A (MAO-A) moclobemide." (PMID 23533900, 2013).
behavior (7 papers, 2012 to 2022). The internally coordinated responses (actions or inactions) of animals (individuals or groups) to internal or external stimuli, via a mechanism that involves nervous system activity. "For instance, it was suggested that children who suffered early trauma and have the MAOA genotype that confers low levels of MAOA enzyme are more likely to develop antisocial behavior in adulthood than maltreated children with a high-activity MAOA genotype." (PMID 34881779, 2022). "So far, one of the most studied G × E interactions in relation to antisocial behavior involves a 30 bp length polymorphic region (LPR) in the monoamine oxidase A (MAOA) gene and exposure to childhood maltreatment." (PMID 30569215, 2019). "Although the low-MAOA genotype on its own did not significantly increase the risk of developing antisocial behavior, it increased the risk for developing antisocial behavior among males who suffered maltreatment." (PMID 31681122, 2019). "Initial findings, such as MAOA x childhood maltreatment in the development of antisocial behavior or DAT1 × maternal prenatal smoking, have not always been replicated." (PMID 23215821, 2013).
colon cancer (7 papers, 2014 to 2025). "When NMI was administered to a mouse model of colon cancer, both albumin and MAOA were detected by mass spectrometry within the fluorescent ~ 65 kD band of tumor lysate." (PMID 39904854, 2025). "Similar to our findings, continuously downregulated MAOA was also found in different colon tumours." (PMID 36902343, 2023). "Further studies in a colon cancer mouse model found the ~ 65 kD SDS-PAGE band, bound to NMI, contained both MAOA and albumin proteins by mass spectrometry." (PMID 39904854, 2025). "Additionally immunohistochemical detection of colon cancer micro array revealed that the expression of serotonin metabolism-related enzymes (TPH1, SERT, MAOA, and MAOB) were overexpressed in human colon cancer tissues than in the adjacent normal tissues." (PMID 34006301, 2021). "Recent studies have shown that immune-cell-derived MAOA promotes an immunosuppressive tumor microenvironment by disrupting T cell and macrophage differentiation in mice, and that combining MAOI and anti-PD-1 treatments resulted in synergistic tumor suppression in melanoma and colon cancer." (PMID 36860320, 2023).
melanoma (7 papers, 2018 to 2024). A malignant, usually aggressive tumor composed of atypical, neoplastic melanocytes. "For example, MAOI significantly synergized with anti-PD-1 to suppress tumor growth in mice, and MAOA expression levels dictated the survival of patients with melanoma who received anti-PD-1 therapy." (PMID 38349393, 2024). "In our study, we found that MAOI treatment synergised with anti-PD-1 treatment in suppressing syngeneic mouse tumor growth, and that intratumoral MAOA gene expression levels dictated poor patient survival in melanoma patients receiving anti-PD-1 therapy." (PMID 34112755, 2021). "Thus, the correlation between the expression of MAOA in melanoma/lung adenocarcinoma and the abundance of CD8+ T infiltration/M2-type macrophage was obtained." (PMID 38349393, 2024). "Furthermore, the results of bioinformatics analysis also demonstrated a significant positive correlation between the expression of MAOA and the immune infiltration of M2 macrophages in melanoma and lung adenocarcinoma." (PMID 38349393, 2024). "Therefore, thanks to this cross-validation among different databases, MAOA, PARP1 and TYR represent the best CMT with significant differential expression in melanoma vs. control biopsies." (PMID 34199192, 2021). "The results of bioinformatics analysis also demonstrated a significant negative correlation between the expression of MAOA and the immune infiltration of CD8+ T cells in melanoma and lung adenocarcinoma." (PMID 38349393, 2024).
insomnia (6 papers, 2022 to 2025). A sleep disorder characterized by difficulty in falling asleep and/or remaining asleep. "Rising melatonin levels in ApoE4 cells occur with down-regulation of MAOA expression, which affects metabolic enzymes through its precursor, serotonin, to cause insomnia." (PMID 39410900, 2025). "We could predict the role of VVO in modulating the serotonergic synaptic pathway in the treatment of insomnia, and this modulation was associated with MAOB, MAOA, PTGS2, HTR2A, and SLC6A4." (PMID 40004189, 2025). "In summary, our research findings have elucidated that VVO treats insomnia through a variety of components and multiple targets, with MAOB, MAOA, SLC6A4, HTR2A, and others at serotonergic synapses playing a vital role in the process of VVO treating insomnia." (PMID 40004189, 2025). "The results from the PPI analysis show that the targets of VVO for the treatment of insomnia mainly involve MAOB, DRD2, MAOA, IL1B, PTGS2, HTR2A, SLC6A4, and ESR1." (PMID 40004189, 2025).
alcohol use disorder (5 papers, 2018 to 2025). "From a clinical point of view, inconstant hypermethylation of the DAT was also reported in the post-exposure withdrawal phase of alcohol use disorder, while methylation of MAOA and hypomethylation of NR2B and GDAP1 were observed in positive relationship to the severity of the alcohol use disorder." (PMID 41153345, 2025).